SQSTM1 (sequestosome 1)
Diseases named in the same sentence as SQSTM1 in open-access papers (continued):
Sharing a sentence is not in itself a finding about the gene and the disease.
neuroblastoma (6 papers, 2016 to 2025). Neuroblastoma (NB) is the most common solid, extracranial childhood tumor. "Western blot analysis of human neuroblastoma cell lysates showed that 30 μM UA for 24 h caused a marked decrease in protein levels of sequestosome-1 (SQSTM1) and microtubule-associated protein light chain 3 (LC3) upon UA treatment." (PMID 36576642, 2023). "This situation parallels the conditions seen in our in vitro experiments in which p62/SQSTM1 levels were increased in neuroblastoma cells transiently transfected with mHtt after acute LM11A-31 treatment." (PMID 39592326, 2025). "We found a significant increase in the expression of p62/SQSTM1 mRNA and protein following mitophagy induction in human neuroblastoma SH‐SY5Y cells." (PMID 26509433, 2016). "However, LM11A-31 increased p62/SQSTM1 levels along with other autophagy markers and increased autophagic flux in ‘neuron like’ human neuroblastoma cells containing mHtt indicating autophagic activity." (PMID 39592326, 2025). "We identified levels of the late autophagosome marker LC3-II and SQSTM1/p62 decreased in the prion peptide-treated group in a dose-dependent manner compared with the control group through western blot analysis in human neuroblastoma cells and mouse primary neuron cells." (PMID 27102156, 2016). "As demonstrated in neuroblastoma cells, the asymmetric distribution of pericentrosomal CD133 and nuclear β-catenin cooperatively suppressed autophagic activity in a nascent daughter cell during cytokinesis by inhibiting p62/SQSTM1 expression." (PMID 38532366, 2024).
acute promyelocytic leukemia (5 papers, 2016 to 2025). An aggressive form of acute myeloid leukemia (AML), characterized by arrest of leukocyte differentiation at the promyelocyte stage, due to a specific chromosomal translocation t(15;17) in myeloid cells. "This constitutive nucleocytoplasmic SQSTM1 shuttling is in agreement with our previous finding that SQSTM1 associates with promyelocytic leukemia bodies." (PMID 27391408, 2016). "Another study found that resveratrol might control autophagy in human lymphoblastic leukemia and human promyelocytic leukemia cells, as evidenced by higher levels of the proteins LC3-II and p62/SQSTM1." (PMID 35566016, 2022). "Similarly, in acute promyelocytic leukemia, ROS-induced HMGB1 translocation facilitates autophagic degradation of the oncogenic PML–RARα fusion protein through interactions with the ubiquitin-binding adaptor p62/SQSTM1, thereby enabling cell differentiation." (PMID 41465435, 2025).
bladder cancer (5 papers, 2019 to 2026). "Taken together, these results suggest that silencing YTHDC1 suppresses autophagy to promote cisplatin resistance and DNA repair via destabilizing SQSTM1 in bladder cancer." (PMID 37070134, 2023). "However, despite this activation, treatment with sunitinib led to the accumulation of p62/SQSTM1 protein in bladder cancer cells, implying impaired lysosomal degradation or incomplete autophagolysosome formation." (PMID 39272847, 2024). "It was reported that LncRNA H19 derived from TAMs could stabilize ULK1 expression by increasing the expression of LC3-II/I and decreasing SQSTM1/p62 levels, thereby activating bladder cancer cell autophagy." (PMID 39394189, 2024). "Targeting the ‘writers’ and ‘erasers’: In cellular models such as bladder cancer, OGT KD consistently up‐regulates autophagic flux, evidenced by increased LC3‐II lipidation and decreased p62/SQSTM1 accumulation." (PMID 41540817, 2026). "C-2 exhibits cytotoxic effect on bladder cancer cells, and JNK activated by C-2 triggers autophagy and up-regulates SQSTM1/p62 proteins, contributing to activation of Nrf2 pathway." (PMID 31685029, 2019).
cardiomyopathy (5 papers, 2022 to 2023). A disease of the heart muscle or myocardium proper. "Autophagy upregulation, elevated MAP1LC3-II and lowered p62/SQSTM1 expression were also associated with Sirt3 signaling in diabetic mice with cardiomyopathy." (PMID 35938164, 2022). "Given our results, which demonstrate mislocalization of SQSTM1 in three independent ALPK3 pathogenic variants, and the growing number of ALPK3 variants linked to HCM15,16, our findings point to a central role for disrupted sarcomeric homeostasis in cardiomyopathy." (PMID 39196058, 2023).
type 2 diabetes (5 papers, 2017 to 2024). "When D-BHB was administered after the coma, SQSTM1/p62 degradation was enhanced and ULK1 S317 phosphorylation was reduced, increasing cell survival." (PMID 33173467, 2020). "In a rat type 2 diabetes model, p62/SQSTM1 was increased and reduced levels of autophagy markers were observed in mouse glomerular lysates 28 days after streptozotocin injection." (PMID 28443030, 2017). "However, at 24 h D-BHB reduced the increase in LC3-II induced by coma in both brain regions, while no change in SQSTM1/p62 was found." (PMID 33173467, 2020).
Ataxia (4 papers, 2020 to 2025). Ataxia refers to impaired coordination of voluntary muscle movement. "In the presented case, we describe a patient from north of Iran who presented with progressive cerebellar ataxia and vertical gaze palsy due to homozygous SQSTM1 mutation detected by WES (Whole Exome Sequencing)." (PMID 35957775, 2022). "In the past decade, studies have shown that mutations on SQSTM1 gene are associated with several diseases including Paget's disease of bone (PDB), liver cancer, breast cancer, obesity, diabetes, and neurodegenerative diseases (including Ataxia, Dystonia, And Gaze Palsy, Childhood‐Onset)." (PMID 35957775, 2022).
cervical carcinoma (4 papers, 2021 to 2022). A carcinoma arising from either the exocervical squamous epithelium or the endocervical glandular epithelium. "In HeLa cells (human cervical carcinoma), we observed a significant reduction of the p62/SQSTM1 signal as early as 2 h p.i., which was further disappearing towards the end of infection (6 h p.i.), as well as a slight increase of the LC3BII form in all infected samples." (PMID 34452452, 2021). "Next, we measured the expression of p62 (SQSTM1), which selectively binds to LC3 and undergoes autophagic degradation, in cervical carcinoma cells, while the level of p62 was reduced by MAC." (PMID 36499465, 2022).
cholestasis (4 papers, 2018 to 2024). Impairment of the bile flow caused by obstruction within the liver, or outside the liver in the bile duct system. "In addition, PHB2 can form a ternary protein complex with SQSTM1/p62 and LC3, which results in LC3 being loaded onto the damaged mitochondria during cholestasis-induced mitophagy." (PMID 39639053, 2024). "Furthermore, it has been suggested that PHB2 is required for cholestasis-induced mitophagy, wherein PHB2 recruits LC3 to the damaged mitochondria via interaction with p62/SQSTM1 and LC3." (PMID 32751272, 2020). "In conclusion, we suggest that PHB2 is essential to cholestasis-induced mitophagy in the cholestatic liver via directly binding the LC3 and may interact with SQSTM1 to recruit LC3 into the impaired mitochondria." (PMID 29416008, 2018).
colitis (4 papers, 2016 to 2025). Inflammation of the colon. "In addition, treatment with HU 308 also significantly increased the LC3-II/LC3-I ratio and Beclin-1 and decreased SQSTM1 in colon from DSS-induced colitis mice." (PMID 27611972, 2016). "p62/SQSTM1 targets claudin-2 for selective autophagy in stressed intestinal epithelium and protects mice from DSS-induced colitis." (PMID 39809743, 2025).
glaucoma (4 papers, 2016 to 2023). Increased pressure in the eyeball due to obstruction of the outflow of aqueous humor. "A cohort of 308 NTG patients and two control cohorts (157 normal controls and 1098 population controls) were tested for glaucoma-causing mutations in the coding sequences of the SQSTM1 gene using automated Sanger DNA sequencing." (PMID 27275741, 2016). "In this report we investigated the possible role of mutations in SQSTM1 in NTG pathogenesis by testing a large cohort of NTG patients for glaucoma-causing mutations." (PMID 27275741, 2016). "Future studies of larger cohorts with more extensive mutation detection strategies (i.e. assessing both coding and regulatory sequences) might have the power to identify rare glaucoma-causing SQSTM1 variants." (PMID 27275741, 2016). "Finally, the ultimate approach to investigate pathogenicity would be to generate a transgenic animals with rare SQSTM1 variants to see if they develop glaucoma." (PMID 27275741, 2016). "Consequently, we investigated SQSTM1 for glaucoma-causing mutations in a cohort of NTG patients." (PMID 27275741, 2016). "Other proteins associated with autophagy that were found to be down regulated during glaucoma are sequestosome-1 (p62) (a scaffold that targets ubiquitinated proteins for autophagic degradation), scCTSB (a lysosomal protein), and LC3B-II." (PMID 36674805, 2023). "An alternative way to support a link between mutations in SQSTM1 and NTG would be to compare inheritance of the detected mutations with the inheritance of glaucoma in family members." (PMID 27275741, 2016).
lysosomal storage disease (4 papers, 2020 to 2024). A metabolic disorder caused by mutations in proteins critical for lysosomal function, including lysosomal enzymes, lysosomal integral membrane proteins, and proteins involved in the post-translational modification and trafficking of lysosomal proteins. "Module PHH:17 (annotated for GO:CC lysosome and includes SQSTM1) is also found to be preserved and is activated by fluoxetine, a known phospholipidosis inducer." (PMID 34626214, 2021). "Lysosomes hold potential as an attractive target for therapeutic intervention in ALS, as in addition to VCP, several other ALS associated genes have a role in lysosomal homeostasis (C9orf72, TARDBP, TMEM106B, TBK1, OPTN, SQSTM1) and several lysosomal storage diseases manifest neurological features." (PMID 39593143, 2024). "Similarly to OPTN and SQSTM1, also VCP and PFN1 share common roles in autophagic degradation raising the hypothesis of a common pathogenic mechanism affecting the formation and clearance of misfolded proteins in PDB, ALS and, more generally, in lysosomal storage diseases." (PMID 36035996, 2022).
muscular dystrophy (4 papers, 2015 to 2023). Muscular dystrophy (MD) refers to a group of more than 30 genetic diseases characterized by progressive weakness and degeneration of the skeletal muscles that control movement. "Although depicting a selective pattern of muscle involvement—as with other muscular dystrophies—was difficult, prominent muscular fatty infiltration in the proximal limbs, with sparing of the anterior lower legs, may suggest isolated SQSTM1 non-sense mutation-associated myopathy." (PMID 36998782, 2023). "Elevated p62/SQSTM1 and nuclear enrichment of Nrf2 were identified in muscle biopsies from the corresponding muscular dystrophy patients, validating the disease relevance of our Drosophila model." (PMID 25996830, 2015). "Muscular dystrophy caused by INPP5K mutations shows features suggestive of autophagy inhibition, including the accumulation of rimmed vacuoles, p62/SQSTM1, and αB-crystallin, but whether autophagy is impaired remains unresolved." (PMID 33119550, 2021). "The Drosophila melanogaster model was used to study the mutations in lamins identified in muscular dystrophy patients, showing that aggregation of cytoplasmic lamins are associated with elevated levels of GSH and NADPH, and with elevated p62/SQSTM1, and nuclear enrichment of NrF2, leading to RS." (PMID 28981461, 2017).
steatosis (4 papers, 2017 to 2023). Increased lipid within the cytoplasm of cells. "Recent reports indicate that the measurement of serum p62/SQSTM1 levels has the potential to serve as a biomarker for the diagnosis of patients with steatosis and inflammation, indicative of NASH stage." (PMID 37958873, 2023). "However, these properties of FXR indicate the potent contribution to the protection against fatty and even non-fatty livers from surgical stress and/or injury and to improve steatosis via p62/SQSTM1 and SHP in various clinical settings." (PMID 28086800, 2017). "The present study is the first to demonstrate the relevance of FXR-p62/SQSTM1 and -SHP in the protection against injury of hepatocytes and post-PH liver, especially with steatosis." (PMID 28086800, 2017). "Lactucin and lactucopicrin target trifunctional enzyme subunit alpha (HADHA), disintegrin, metalloproteinase domain-containing protein 17 (ADAM17), Sequestosome-1 (SQSTM1), and lysosomal acid glucosylceramidase (GBA) genes to promote fatty acid oxidation, and then ameliorate FFA-induced steatosis." (PMID 36558977, 2022).
Stroke (4 papers, 2021 to 2025). Sudden impairment of blood flow to a part of the brain due to occlusion or rupture of an artery to the brain. "With respect to complications of CVD, a recent study revealed that p62/SQSTM1 regulates oxidative and ER stress, and inflammation following cerebral I/R injury, with elevated p62 levels being associated with worse stroke outcomes." (PMID 41300435, 2025). "Similarly, immunoblotting showed a marked increase in p-AMPKα, p-ULK1 (Ser 317), and active caspase-3 plus a greater reduction in p62/SQSTM1, p-mTOR, mTOR, p-S6, p-4E-BP, and p-ULK1 (Ser757) in the ipsilateral cerebral cortex of CrT–/y mice 24 hours after stroke." (PMID 34324436, 2021).
thyroid cancer (4 papers, 2019 to 2023). "Recent studies have demonstrated that SQSTM1 promotes cell growth and induces autophagy in thyroid cancer by modulating AKT/mTOR signaling pathway." (PMID 35711939, 2022).
asthma (3 papers, 2021 to 2025). "Thus, HSPA5/A2M could be exploited as novel drug targets for childhood asthma while SQSTM1 might serve as a potential target or therapeutic responder." (PMID 41550933, 2025). "Interestingly, expression of BECN1 and ATG5 has been found to be increased, together with reduced expression of SQSTM1, in the large airway smooth muscle of patients with asthma compared with healthy individuals without asthma." (PMID 34572117, 2021).
B-cell lymphoma (3 papers, 2018 to 2022). "T-cell receptor-mediated NF-κB activation in B-cell lymphoma/leukemia is linked with the autophagy adaptor p62/SQSTM1, which modulates the NLRP3-inflammasome activation and IL-1β production in macrophages." (PMID 31277291, 2019).
fibrosis (3 papers, 2022 to 2023). the formation of excess fibrous connective tissue in an organ or tissue in a reparative or reactive process. "Caveolin-1 has been shown to inhibit fibroblast autophagy by regulating Sequestosome 1, which decreases intestinal fibrosis in CD31." (PMID 37550393, 2023). "Conversely, a research group that analyzed melatonin properties in NAFLD‐derived fibrosis reported a raise in autophagosomes, mitofusin 2 (Mfn2), and a decrease in cytoplasmic SQSTM1/p62 levels." (PMID 35404472, 2022). "Using a DSS fibrosis model and in vitro studies with primary intestinal fibroblasts, their work shows that Caveolin-1 (CAV1) increases the expression of SQSTM1/p62 and inhibits autophagy, thus preventing fibroblast transdifferentiation and avoiding the accumulation of α-SMA and ECM." (PMID 37397491, 2023).
heart failure (3 papers, 2021 to 2025). Inability of the heart to pump blood at an adequate rate to meet tissue metabolic requirements. "In contrast to heart failure from other causes, this NAD+ deficiency is due to induction of NNMT by SQSTM1-NF-κB signaling." (PMID 38212381, 2024). "Deficient autophagy reduces NAD+ availability in cardiomyocytes via a SQSTM1-NF-κB-NNMT axis, contributing to mitochondrial dysfunction and heart failure." (PMID 38212381, 2024).
Hyperglycaemia (3 papers, 2019 to 2025). "Furthermore, in diabetic wound-healing models, hyperglycemia-induced SQSTM1 loss impairs autophagic flux, leading to ACSL4 accumulation and enhanced ferroptosis." (PMID 40843317, 2025). "Conversely, LC3 staining was reduced, along with p62/SQSTM1 accumulation in the cytoplasm of glomerular cells after eight weeks, confirming a disruption of autophagic flux in glomeruli under long‐term hyperglycaemia." (PMID 32583573, 2020). "Hyperglycaemia downregulates autophagy and accumulates P62/SQSTM1 due to lysosomal dysfunction, which induces apoptosis." (PMID 31814880, 2019). "Given its role as an upstream modulator of ferroptosis, the increased expression of SQSTM1 in these cells is likely indicative of a compensatory autophagic mechanism aimed at mitigating ferroptotic signaling and supporting neuronal survival under conditions of hyperglycemia and oxidative stress." (PMID 40843317, 2025).
Insulin resistance (3 papers, 2015 to 2023). Increased resistance towards insulin, that is, diminished effectiveness of insulin in reducing blood glucose levels. "We found that phosphorylation of sequestosome-1 was clearly increased under palmitate-induced insulin resistance, compared to the slight increase in TNF-a-induced insulin resistance." (PMID 35055191, 2022). "Subsequently, we examined whether Sqstm1 phosphorylation levels were affected by the onset of insulin resistance." (PMID 36901549, 2023).
ischemia (3 papers, 2018 to 2022). A hypoperfusion of the BLOOD through an organ or tissue caused by a PATHOLOGIC CONSTRICTION or obstruction of its BLOOD VESSELS, or an absence of BLOOD CIRCULATION. "For age-related ischemia/reperfusion, SQSTM1 forms a complex with RIP1–RIP3, which contributes to myocardial necroptosis." (PMID 35957699, 2022). "A previous study demonstrated that the autophagy-related proteins microtubule-associated proteins light chain 3 (LC3B) and sequestosome 1 (SQSTM1, p62) were significantly upregulated in penumbra neurons after focal cerebral ischemia, whether ischemia-induced autophagy was beneficial or detrimental." (PMID 29970982, 2018).
kidney cancer (3 papers, 2015 to 2022). Primary or metastatic malignant neoplasm involving the kidney. "Furthermore, Sqstm1 has been identified as a pathogenic target of 5q copy number gains in kidney cancer." (PMID 26483381, 2015). "TBK1 contributes to kidney cancer cell growth by phosphorylating p62/SQSTM1 on Ser366, thus stabilizing p62." (PMID 33142830, 2020).
lymphoma (3 papers, 2017 to 2025). A malignant (clonal) proliferation of B- lymphocytes or T- lymphocytes which involves the lymph nodes, bone marrow and/or extranodal sites. "Specifically, STAT3 inhibition also serves as a possible therapeutic target for lymphomas with the SQSTM1-ALK variant translocation." (PMID 28665943, 2017). "Compared with those in control tissue, lymphoma showed significant increases of in LC3B (LC3BI represents early autophagy, while LC3BII represents autophagic flux), autophagy related 14 (Atg14) and Beclin-1 levels, and a decrease in p62 (sequestosome 1) levels." (PMID 40296899, 2025).
motor neuron disease (3 papers, 2017 to 2022). "MATR3-related pathology, encompassing myopathy and motor neuron disease, represents an illustrative example of multisystem proteinopathy (MSP), such as other diseases associated to mutations in VCP, HNRNPA2B1, HNRNPA1, and SQSTM1 genes." (PMID 34659085, 2021).
osteoarthritis (3 papers, 2020 to 2023). A noninflammatory degenerative joint disease occurring chiefly in older persons, characterized by degeneration of the articular cartilage, hypertrophy of bone at the margins and changes in the synovial membrane. "MicroRNA-17-5p was shown to promote osteoarthritis progression through binding to p62/SQSTM1." (PMID 37702097, 2023).
osteoporosis (3 papers, 2015 to 2020). A condition of reduced bone mass, with decreased cortical thickness and a decrease in the number and size of the trabeculae of cancellous bone (but normal chemical composition), resulting in increased fracture incidence. "For example, previously we demonstrated that administration of p62/SQSTM1-encoding plasmid reduced chronic inflammation and alleviated osteoporosis and metabolic syndrome in animal models." (PMID 30153656, 2018).